IL2 (interleukin 2)
Diseases named in the same sentence as IL2 in open-access papers (continued):
Sharing a sentence is not in itself a finding about the gene and the disease.
endometrial cancer (3 papers, 2010 to 2024). Primary or metastatic malignant neoplasm involving the endometrium (mucous membrane that lines the endometrial cavity). "To validate our findings on the protein level, we first studied production of CD8+-associated cytokines IFN-γ, TNF-α, and IL-2 in endometrial cancer cytotoxic TIL." (PMID 32471032, 2020). "The administration of low doses of IL-2 might therefore be a valid therapeutic option to increase IDCC in heavily pretreated endometrial cancer patients." (PMID 20700124, 2010). "To validate this, we performed a flow cytometry experiment of PMA/ionomycin-activated and unstimulated CD8+ TIL from endometrial cancer digests including these markers plus IFN-γ, TNF-α, and IL-2 as an internal control." (PMID 32471032, 2020).
esophagogastric junction adenocarcinoma (3 papers, 2015 to 2023). "We evaluated zolbetuximab in combination with ZA and IL-2 in patients with advanced or metastatic G/GEJ adenocarcinoma to determine activation and kinetic profiles of immune cell populations induced by ZA with or without IL-2." (PMID 36607429, 2023). "Another phase I study, PILOT, included IMAB362 plus zoledronic acid (ZA) and a low-to-medium dose interleukin 2 (IL-2) in patients with advanced GC and esophagogastric junction adenocarcinoma." (PMID 35053454, 2022). "The objective of this study was to determine whether pretreated patients with advanced G/GEJ adenocarcinoma exert proficient ADCC and whether they further benefit from ZA and IL-2." (PMID 36607429, 2023).
hemophilia A (3 papers, 2014 to 2021). The most common form of hemophilia characterized by spontaneous or prolonged hemorrhages due to factor VIII deficiency. "In our previous studies, administration of IL-2/IL-2mAb complexes prevented anti-FVIII immune responses in hemophilia A mice following gene or protein replacement therapy." (PMID 24432019, 2014). "To further improve the therapeutic efficacy, we combined B-cell depletion using anti-CD20 with in vivo Treg cell expansion using IL-2/IL-2mAb complexes+rapamycin to treat hemophilia A inhibitor mice." (PMID 24432019, 2014). "Moreover, the IL-2 mutein prevented antibody response to FVIII in a mouse model of hemophilia A, further supporting that Tregs responding to an attenuated IL-2 mutein exert immune suppressive effects." (PMID 33854514, 2021). "Anti-CD20 targets a variety of B-cells (pre-B-cells to mature/memory cells); therefore, we investigated the impact of B-cell depletion on anti-FVIII immune responses in hemophilia A mice using anti-CD20 combined with regulatory T (Treg) cell expansion using IL-2/IL-2mAb complexes plus rapamycin." (PMID 24432019, 2014). "Hemophilia A mice were treated with IL-2/IL-2mAb complexes+ rapamycin+anti-CD20+FVIII; IL-2/IL-2mAb complexes+ rapamycin+FVIII; anti-CD20+FVIII; and FVIII alone." (PMID 24432019, 2014). "Our previous studies using IL-2/IL-2mAb complexes alone showed five to sevenfold expansion of highly suppressive Treg cells in vivo, which induced long-term tolerance to FVIII in unprimed hemophilia A mice following gene therapy." (PMID 24432019, 2014). "Since anti-CD20 treatment can partially modulate anti-FVIII immune responses in hemophilia A mice, we investigated whether a combination therapy using anti-CD20 to deplete B-cells and IL-2/IL-2mAb complexes to expand Treg cells can more consistently reduce anti-FVIII responses." (PMID 24432019, 2014). "Thus, we adopted a treatment strategy that included rapamycin with IL-2/IL-2mAb complexes to enhance Treg cell function in vivo for targeting T-cell-mediated immune responses and induction of FVIII-specific tolerance in hemophilia A mice with pre-existing antibodies." (PMID 24432019, 2014). "Although no clinical trials have been initiated so far, IL-2/IL-2mAb complexes have high potential as a clinically feasible strategy; however, IL-2/IL-2mAb complex single treatment in the hemophilia A “inhibitor” mice only transiently reduced neutralizing antibody titers during treatment." (PMID 24432019, 2014).
hookworm infection (3 papers, 2011 to 2012). "However, in contrast to the increased accumulation of IL-2, IL-15 and ALDH1A2, accumulation of mRNA encoding the innate Th17-inducing and stabilising IL-23 was potently suppressed by hookworm infection, potentially neutralising the impact of these Th17 promoting cytokines." (PMID 22346753, 2012). "Our results show that experimental hookworm infection leads to a strong systemic and mucosal Th2 (IL-4, IL-5, IL-9 and IL-13) and regulatory (IL-10 and TGF-β) response, with some evidence of a Th1 (IFN-γ and IL-2) response." (PMID 22346753, 2012). "Levels of QE65-specific IL-2, IFN-γ or IL-17A did not appear to change after hookworm infection or challenge." (PMID 21949691, 2011).
hypercoagulability (3 papers, 2009 to 2022). "Biologically hypercoagulability as a paraneoplastic phenomenon is explained by circulating higher levels of substances as interleukin-2, produced by cancer-cells and increased autoantigens, originating from dying cancer cells." (PMID 19946524, 2009).
hyperlipidemia (3 papers, 2019 to 2024). "In contrast, reduced secretion of Treg-inducing cytokine IL-2 was detected in hyperlipidemia mice injected with HSP65, which can be restored by YQHP rather than simvastatin." (PMID 30713570, 2019).
hyperthyroidism (3 papers, 2007 to 2024). Overactivity of the thyroid gland resulting in overproduction of thyroid hormone and increased metabolic rate. "We identified a significant causal association between interleukin-2 (IL-2) and stem cell growth factor beta (SCGF-β) with hyperthyroidism (OR = 1.134, 95% CI: 1.037–1.241, p = 0.006; OR = 1.106, 95% CI: 1.019–1.202, p = 0.017, respectively)." (PMID 38872961, 2024). "In group C, four participants withdrew during Step I because of intolerance to IL-2 injections, one withdrew during Step II because he/she wanted to restart HAART, two were terminated because of the development of hyperthyroidism, and one was terminated because of low CD4+ T cell concentrations." (PMID 17260026, 2007).
Hypoglycemia (3 papers, 2013 to 2025). A decreased concentration of glucose in the blood. "Both IL-2 and IFNγ are also critical in Dgal-sensitized models of superantigen-induced shock as IL-2 deficient mice were resistant to SEB-induced shock and antibodies to IFNγ inhibited SEB-induced weight loss and hypoglycemia." (PMID 24064719, 2013). "However, hypoglycemia markedly reduced the expression of interferon-gamma (IFNγ) and, to a lesser degree, tumour necrosis factor-alpha (TNFα), key indicators of effector function, while interleukin-2 (IL-2) production was unaffected." (PMID 40575013, 2025).
inflammatory skin disease (3 papers, 2015 to 2024). Inflammatory skin disorders covers a broad category that includes many conditions ranging in severity, from mild itching to grave medical health complications These disorders are common in people of all ages and races. "Tacrolimus is an immunomodulator that prevents the production of interleukin-2 (IL-2) and consequent T-cell activation, which controls the inflammatory process and is used in many inflammatory skin diseases." (PMID 39759595, 2024). "Furthermore, gal-7 was shown to inhibit expression of interleukin-2 and interferon-γ mRNA in Jurkat cells and was proposed as a potential new immunosuppressive therapy against inflammatory skin diseases." (PMID 27136536, 2016).
intervertebral disc degeneration (3 papers, 2020 to 2024). "Hanaei investigated the polymorphism of IL-2 +166G/T, IL-2 -330G/T, IL-12−1188A/C, IFN-γ+847A/T, IL-4 (rs2243248 (1098G/T), rs2243250 (590 C/T), rs2070874 (33 C/T)), and 1 SNP IL-4RA (rs180275, þ1902 A/G) in patients with intervertebral disc degeneration using PCR." (PMID 37893088, 2023).
laryngeal carcinoma (3 papers, 2009 to 2024). Carcinoma that arises from the laryngeal epithelium. "We assessed the serum levels of cytokines (IL–1, IL–2,IL–4, IL–6, IL–8, IL–10, IFN–gamma, TNF–alpha, GM–CSF), chemokines (MCP–1 and MIP–1alpha)and growth factors (VEGF and bFGF) in laryngeal cancer patients before, during and after surgery." (PMID 20108543, 2009). "Further experimentation showed that both the percentage and number of Th1 cells (including IFN-γ- and IL-2-secreting cells) were increased in T cell and DC-TSL co-culture, which strongly supports the choice of TSL-pulsed as a promising CTL activator against laryngeal cancer." (PMID 26795730, 2016).
macular degeneration (3 papers, 2019 to 2024). Loss of vision in the central portion of the retina (macula), secondary to retinal degeneration. "In conclusion, IL‐2 played an important role on the fibrosis of macular degeneration." (PMID 31608440, 2019).
malignant mesothelioma (3 papers, 2009 to 2024). A malignant neoplasm of the pleura or peritoneum, arising from mesothelial cells. "Similarly, in a study involving recombinant VACV expressing interleukin-2 (IL-2), direct intratumoral injection resulted in neutrophil aggregation and tumor necrosis in some patients with malignant mesothelioma." (PMID 39697335, 2024).
meningitis (3 papers, 2019 to 2025). A disorder characterized by acute inflammation of the meninges of the brain and/or spinal cord. "Of the 13 measured, 11 (GM-CSF, IFNγ, IL-1α, IL-1Β, IL-2, IL-4, IL-6, IL-10, IL-12, IL-18, and TNF-α) exhibited higher concentrations in the saliva of pigs with meningitis and S. suis infection." (PMID 40284818, 2025). "When a panel of cytokines (including GM-CSF, IFNγ, IL-1α, IL-1β, IL-1ra, IL-2, IL-4, IL-6, IL-8, IL-10, IL-12, IL-18, and TNF-α) was measured in saliva from healthy pigs and in pigs with meningitis and S. suis infection, upregulation of several cytokines was observed in the diseased animals." (PMID 40284818, 2025). "At meningitis diagnosis, stimulation with cryptococcal capsule component, glucuronoxylomannan (GXM) elicited consistently lower frequencies of CD4+ and CD8+ T cell memory subsets expressing intracellular cytokines (IL-2, IFN-γ, and IL-17) among subjects who subsequently developed CM-IRIS." (PMID 31126019, 2019).
mucositis (3 papers, 2015 to 2022). Mucositis is inflammation and damage of the mucous membranes lining the mouth and other parts of the gastrointestinal (GI) tract. "Since one of the main mucositis causes is increasing inflammatory markers such as IL-2, IL-6 and etc, anti-inflammatory effects of atorvastatin is justifiable." (PMID 36420333, 2022).
myasthenia gravis (3 papers, 2006 to 2017). Myasthenia gravis (MG) is a rare, clinically heterogeneous, autoimmune disorder of the neuromuscular junction characterized by fatigable weakness of voluntary muscles. "Two additional serious irAEs attributed to IL-2 were the development of myasthenia gravis in one patient and Guillain-Barre syndrome in one patient." (PMID 29254506, 2017).
myelofibrosis (3 papers, 2022). A partial or complete replacement of the bone marrow stroma by fibrous tissue. "Studies about inflammatory cytokines indicated that the levels of IL6, IL2, and sIL2a were elevated during the progression from PV/ET to myelofibrosis." (PMID 36061178, 2022).
neuromyelitis optica spectrum disorder (3 papers, 2017 to 2020). "The prevalence of Abs against both IL-2 epitopes was additionally assessed in 34 samples of patients affected by neuromyelitis optica spectrum disorder (NMOSD)." (PMID 29379122, 2018). "Here, we investigated the levels of antibodies (Abs) directed against IL-2 and HERV-Wenv in 108 MS patients, 34 patients affected by neuromyelitis optica spectrum disorder (NMOSD), and 137 healthy controls (HCs)." (PMID 32244639, 2020).
neuropathic pain (3 papers, 2014 to 2023). Chronic pain caused by damage to nerve fibers. "Repeated EA interventions have a time-dependent cumulative analgesic effect in neuropathic pain rats, which is closely associated with its regulatory effects on NK cells, splenic IL-2, β-EP, and plasma IL-2, IL-1β, IFN-γ and TGF-β levels." (PMID 25158599, 2014). "In brief, we identified four hub genes, namely IL2, CCR3, CXCL1, CCL4, and SELL, as potential diagnostic markers that may be useful for the diagnosis of neuropathic pain and further understanding of the underlying mechanisms of neuropathic pain risk genes." (PMID 37123369, 2023). "Interestingly, IL-2 has been reported to exert an analgesic effect in an experimental model of neuropathic pain." (PMID 33413508, 2021).
orchitis (3 papers, 2021 to 2024). Inflammation of one or both testes due to viral or bacterial infections. "Therefore, cytokines as Il2 were also potentially involved in interstitial fibrosis during orchitis." (PMID 35111154, 2021). "In this study, the mRNA expressions of IL-2, TNF-α, IL-17A, and IL-1β, which have essential roles in inflammatory processes, were elevated in LPS-induced orchitis; however, PHN have been found to reduce their expression." (PMID 38846786, 2024).
osteonecrosis (3 papers, 2017 to 2025). A none disease characterized by death of bone tissue due to a lack of blood supply. "A study assessing the association between 41 proinflammatory cytokines and osteonecrosis by Mendelian randomization identified IL-2 as causally associated with osteonecrosis risk." (PMID 40510588, 2025). "The identification of bFGF, IL-2, and IL-2RA as causally linked to osteonecrosis suggests promising avenues for potential therapeutic interventions." (PMID 38745949, 2024). "The current study has successfully established a causal relationship between bFGF, IL-2, IL-RA, and osteonecrosis from a genetic perspective." (PMID 38745949, 2024). "Moreover, higher circulating levels of IL-2 appear to be suggestively associated with a reduced risk of osteonecrosis." (PMID 38745949, 2024). "It conclusively establishes a causal association between osteonecrosis and bFGF, IL-2, and IL-2RA." (PMID 38745949, 2024). "Notably, the study unequivocally establishes a causal association between bFGF, IL-2, and IL-2RA with osteonecrosis." (PMID 38745949, 2024). "Furthermore, heightened IL-2RA levels were associated with an elevated risk of osteonecrosis (OR=1.386, 95% CI=1.04-1.85, p=0.026), while increased IL-2 levels were linked to a decreased risk (OR=0.688, 95% CI=0.50-0.94, p=0.021, per 1 standard deviation (SD) increase)." (PMID 38745949, 2024). "IL-2 plays a pivotal role in mitigating osteonecrosis and fostering the healing of bone tissue by impacting various cellular processes." (PMID 38745949, 2024). "The study suggests bFGF, IL-2, and IL-2RA as potential therapeutic targets for osteonecrosis treatment." (PMID 38745949, 2024). "The results showed that bFGF, IL-2 and IL2-RA were clinically causally associated with the risk of osteonecrosis (OR=1.942, 95% CI=1.13-3.35, p=0.017; OR=0.688, 95% CI=0.50-0.94, p=0.021; OR=1.386, 95% CI=1.04-1.85, p = 0.026)." (PMID 38745949, 2024). "suggests that IL-2 can hinder osteoclastogenesis, thus indirectly safeguarding bone tissue and aiding in the alleviation of osteonecrosis." (PMID 38745949, 2024). "Previous studies have shown that inflammatory cytokines are increased during the development of steroid-induced osteonecrosis, such as IL-1, IL-2, IL-4, IL-6, IL-10, GM-CSF, IFN-γ, and TNF-α." (PMID 28167850, 2017). "According to our present MR analysis, bFGF in conjunction with IL-2RA may contribute to the development of osteonecrosis, while IL-2 exhibits an opposing effect." (PMID 38745949, 2024). "Similarly, the genetic prediction level of IL-2 demonstrated a negative, albeit not statistically significant, causal effect with drug-induced osteonecrosis (OR=0.507, 95% CI=0.17-1.55, per 1 standard deviation (SD) P=0.232)." (PMID 38745949, 2024). "Restoration of butyrate through FMT or sodium butyrate supplementation alleviated osteonecrosis by modulating inflammatory cytokines, reducing TNF-α and IL-2, and increasing IL-4 expression." (PMID 40510588, 2025). "With the exception of bFGF, IL-2RA, and IL-2, other cytokines such as VEGF, GRO-α, Trail, MIG, IL-7, and IL-17 did not demonstrate any association with osteonecrosis risk in the IVW primary MR analysis or secondary analyses." (PMID 38745949, 2024).
papillary thyroid cancer (3 papers, 2020 to 2023). "This may be a direct effect of IL-2, as there have been reports of IL-2 induced upregulation of MHC class II in neutrophils and of MHC class I in papillary thyroid cancer cells, but at the same time monocyte-derived DCs were found to neither express IL-2Rβ nor respond to IL-2." (PMID 37501121, 2023).
polymyositis (3 papers, 2023 to 2025). A rare idiopathic inflammatory myopathy characterized by symmetric proximal muscle weakness and elevated muscle enzymes. "We suggest that elements located 10–49 kb upstream of the IL21/IL2 locus play an important role in the regulation of the canine genes and that deletion of these elements is a risk factor for polymyositis in Kooiker dogs." (PMID 39746095, 2025). "Our study unequivocally demonstrates the involvement of the IL21/IL2 locus in polymyositis in the Kooiker dog." (PMID 39746095, 2025).
primary biliary cholangitis (3 papers, 2015 to 2024). Primary biliary cholangitis (PBC) is a chronic and slowly progressive cholestatic liver disease of autoimmune etiology characterized by injury of the intrahepatic bile ducts that may eventually lead to liver failure. "Furthermore, IL-2Rα KO mice lost the repressive effect of IL-2 on Th17 cells, showed elevated levels of serum IL-17A, and finally suffered from primary biliary cirrhosis (PBC)." (PMID 26325187, 2015). "In primary biliary cholangitis (PBC), the levels of serum IL-2 were involved in liver inflammation and immune changes." (PMID 36159788, 2022). "The combination of serum IL-2 and TBIL can be a predictor of the progression of liver failure in patients with primary biliary cholangitis, and it is likely to be related to the expression of GM-CSF and G-CSF." (PMID 36159788, 2022).
prostate adenocarcinoma (3 papers, 1998 to 2025). "A moderate correlation was identified only in the prostate adenocarcinoma group for TGF-β (r = 0.54, p = 0.01) and IL-17 (r = 0.42, p = 0.06) as well as for gastric adenocarcinoma (r = 0.40, p = 0.07) for IL-2." (PMID 34518597, 2021). "However, it is well documented that PC3 cells do not secret IL-2 and our gene correlation analysis using GEPIA also confirms that there is no gene expression correlation between P2RX4 and IL-2 in prostate adenocarcinoma but a positive correlation in whole blood." (PMID 40515881, 2025).
prostatitis (3 papers, 2020 to 2023). An infectious or non-infectious inflammatory process affecting the prostate gland. "It is reported that total glucosides of V. officinalis attenuate chronic nonbacterial prostatitis in rat models by reducing the release of IL-2, IL-1β, and TNF-α in the prostate." (PMID 37108306, 2023).
rhinitis (3 papers, 2009 to 2021). An inflammation of the mucous membrane lining the nose, usually associated with nasal discharge. "iNOS is a major producer of NO and plays vital roles in patients with inflammatory diseases, including AD, rhinitis, and pollinosis, when it is stimulated by bacterial lipopolysaccharides or various cytokines, such as IL-1β, IL-2, and TNF-α." (PMID 29088069, 2017).
Rotavirus infection (3 papers, 2022 to 2025). Infection with any of the rotaviruses. "In this study, we aimed to determine the effects of HSP-27, Caspase-3, IL-2, γ-H2AX, HMGB-1, SP-D, and GDH on the pathogenesis of rotavirus infection by using biomarkers of lung and liver injury in neonatal diarrheic calves naturally infected with rotavirus, both in vivo and postmortem." (PMID 41515946, 2025). "The mechanism by which aspirin reduces rotavirus infection may involve the inhibition of rotavirus-induced expression of COX-2, IL-2 and/or IL-10." (PMID 37848986, 2023).